MIR9-2HG (MIR9-2 host gene)
Synonyms: uc.166; EyeLinc1; Visc; LOC645323; ECONEXIN; NDIME; LINC00461; LINC02060
Gene: Long non-coding RNA gene on chromosome 5 (88,408,982 to 88,691,313, reverse strand). Ensembl gene ENSG00000245526.
Gene Ontology:
Biological process: miRNA-mediated post-transcriptional gene silencing
Cellular component: RISC complex
Diseases named in the same sentence as MIR9-2HG in open-access papers:
MIR9-2HG is named in the same sentence as 28 diseases in open-access papers, as found by Europe PMC text mining. Sharing a sentence is not in itself a finding about the gene and the disease.
MIR9-2HG shares sentences with these, for which no sentence is quoted: tumor (16 papers); glioma (13); cancer (9); breast carcinoma (7); colorectal cancer (4); hepatocellular carcinoma (4); non-small cell lung carcinoma (4); albinism (2); lung adenocarcinoma (2); multiple myeloma (2); psychiatric disorder (2); schizophrenia (2); Anxiety (1); autism (1); congenital stationary night blindness (1); gastric cancer (1); glioblastoma (1); head, neck squamous cell carcinoma (1); lung carcinoma (1); metastatic prostate carcinoma (1); nasopharyngeal carcinoma (1); osteosarcoma (1); prostate carcinoma (1); rectal cancer (1); renal cell carcinoma (1); retinal disorder (1); Retinal dystrophy (1); sarcoma (1).